NOTCH3 (notch receptor 3)
Diseases named in the same sentence as NOTCH3 in open-access papers (continued):
Sharing a sentence is not in itself a finding about the gene and the disease.
heart failure (5 papers, 2019 to 2025). Inability of the heart to pump blood at an adequate rate to meet tissue metabolic requirements. "For example, notable genes such as FOXC2 and NOTCH3, identified in familial VV, are also implicated as shared factors in the pathogenesis of heart failure." (PMID 39775444, 2025). "Animal studies in Notch3-deficient mice suggest that Notch3 plays an important role in coronary adaptation to pressure overload and further risk of heart failure." (PMID 37550405, 2023). "Notch3 also regulates vascular tone and flow-mediated dilation of arterial vessels, and adult Notch3 mutant mice show an increased incidence of developing heart failure under angiotensin II–induced hypertensive conditions." (PMID 35998033, 2022). "Notch3−/− mice exhibit higher mortality in response to angiotensin II-induced systemic hypertension and this is reported to be due to an increase in heart failure." (PMID 31868216, 2019). "Although literature has shown that the Notch signaling system exists in myocardial cells and is activated during heart failure, and Notch3 and Notch4 may be the main receptors involved, more studies have reported a close relationship between Notch1 and cardiovascular disease." (PMID 38841263, 2024).
lupus nephritis (5 papers, 2020 to 2026). Glomerulonephritis in the context of systemic lupus erythematosus. "NOTCH3 is overexpressed in the synovial fibroblasts of rheumatoid arthritis patients and in the glomeruli of lupus nephritis." (PMID 41614843, 2025). "In lupus nephritis, rapidly progressive renal disease, and focal segmental glomerulonephropathy, Notch3 is expressed in glomerular podocytes." (PMID 33149805, 2020). "Notch3 was activated in lupus nephritis and extra capillary glomerulonephropathy." (PMID 39910908, 2025). "Notch3 is highly expressed in the nucleus and cytoplasm of podocytes in kidney biopsies of patients with focal segmental glomerulosclerosis (FSGS) and lupus nephritis (LN)." (PMID 33149805, 2020).
meningioma (5 papers, 2023 to 2025). A generally slow growing tumor attached to the dura mater. "NOTCH3 is increasingly implicated for its oncogenic role in many malignancies, including meningiomas." (PMID 40502769, 2025). "In previous studies, NOTCH3 expression has been associated with higher grade, radiation resistance, and recurrence in meningioma." (PMID 40502769, 2025). "While prior work has linked NOTCH3 expression to higher-grade meningiomas and treatment resistance, the metabolic phenotype of NOTCH3 activation remains unexplored in meningioma." (PMID 40502769, 2025). "By upregulating FAO pathways, NOTCH3-expressing meningioma cells may enhance ATP generation while reducing susceptibility to ferroptototic death processes." (PMID 40502769, 2025). "This study is the first to identify an association between NOTCH3 expression, FAO regulation, and ferroptosis resistance in meningioma cells." (PMID 40502769, 2025). "Recently, the NOTCH3 gene has been identified as a driver for tumor growth and resistance to radiation in meningiomas." (PMID 40502769, 2025). "Through scRNA-seq, we demonstrate that NOTCH3 + human meningioma cells exhibit enriched expression of CD36." (PMID 40502769, 2025). "The scRNA-seq data revealed a correlation between NOTCH3 + meningioma cells and clusters-of-differentiation 36 (CD36) expression, indicating that CD36 is enriched in NOTCH3 + cells." (PMID 40502769, 2025). "Utilizing the CH157-MN meningioma model, we demonstrate a shift in lipid metabolism with NOTCH3 ICD overexpression." (PMID 40502769, 2025). "Increased utilization of lipids in NOTCH3 expressing meningiomas poses a metabolic advantage was well as contributes to resistance to ferroptosis, leading increased cell survival in the setting of oxidative stress." (PMID 40502769, 2025). "The lipid metabolism enrichment observed in NOTCH3-expressing patient-derived meningioma cells led us to investigate the direct role of NOTCH3 overexpression using a controlled in vitro model." (PMID 40502769, 2025). "Using the CH157-MN meningioma cell model, we overexpressed NOTCH3 intracellular domain (ICD) and performed untargeted metabolomic, lipidomic, and bulk RNA sequencing analyses as well as functional metabolic assays." (PMID 40502769, 2025). "We established NOTCH3 high and low patient-derived primary meningioma lines and validated NOTCH3 correlates with CD36 expression." (PMID 40502769, 2025). "While this study focuses on mechanistic investigation, further in vivo studies are needed to assess the role of NOTCH3 on meningioma metabolism." (PMID 40502769, 2025). "NOTCH3+ cells are found to be expressed throughout high-grade meningiomas that are resistant to radiotherapy." (PMID 37686527, 2023). "NOTCH3 drives meningioma tumorigenesis and is diffusely expressed in high-grade meningiomas that are resistant to radiation." (PMID 37546798, 2023). "This metabolic profile protects cells from ferroptosis and may be a mechanism to both enhance malignancy and resistance to therapeutic interventions such as sorafenib or cisplatin, portending a poor prognosis in NOTCH3-expressing meningiomas." (PMID 40502769, 2025). "FAO, with adjuvant CPT1a inhibitors, may restore ferroptosis vulnerability in NOTCH3 expressing meningiomas." (PMID 40502769, 2025). "We performed single-cell RNA sequencing on NOTCH3 + human meningioma cell lines." (PMID 40502769, 2025). "Furthermore, considering the clinical diversity of meningioma tumours it is likely that other progenitor cells drive or contribute to meningioma tumorigenesis as well, such as, for example, NOTCH3+ mural cells." (PMID 40672210, 2025). "This metabolic shift may contribute to the malignant behavior observed in NOTCH3 + meningiomas, offering new insight into the biochemical vulnerabilities of these tumors." (PMID 40502769, 2025).
meningioma (continued). "Considering the protection from RSL3 observed in the CH157-MNNOTCH3 ICD, and the low levels of intracellular lipids in this line, we hypothesized NOTCH3 protects meningioma cells from ferroptosis via their increased FAO." (PMID 40502769, 2025). "By comparing OCR between the NOTCH3high PDX2 and NOTCH3low PDX1 primary lines, we show an increase in maximal mitochondrial respiration in the presence of palmitate in NOTCH3high primary cells, suggesting a functional upregulation of lipid metabolism in NOTCH3-expressing meningioma cells." (PMID 40502769, 2025). "In this study, we demonstrate that NOTCH3 promotes a metabolic shift towards FAO, lipid depletion, and resistance to ferroptosis in meningioma cells." (PMID 40502769, 2025). "Furthermore, patient-derived primary meningioma lines stratified by NOTCH3 expression confirmed higher CD36 expression and increased maximal mitochondrial respiration in NOTCH3-high cells in the presence of palmitate, supporting enhanced FAO." (PMID 40502769, 2025). "Meningioma cell states were distinguished by expression of SSTR2A, PDGFRB, and NOTCH3." (PMID 37546798, 2023). "However, the metabolic role of NOTCH3 in meningiomas has not been established." (PMID 40502769, 2025).
multiple sclerosis (5 papers, 2020 to 2025). A progressive autoimmune disorder affecting the central nervous system resulting in demyelination. "The burden test indicated that any autoimmune diagnosis (1.63 [1.14, 2.09], p = 2.665 × 10−3) and multiple sclerosis (3.42 [1.67, 6.02], p = 9.681 × 10−4) are associated with a NOTCH3 cysteine-altering variant in any domain." (PMID 37834922, 2023). "Similar trends were observed analyzing data from the UK Biobank, although multiple sclerosis did show a significant association with NOTCH3 mutations in all domains." (PMID 37834922, 2023). "Analysis of UK Biobank data indicated any autoimmune diagnosis (1.63 [1.14, 2.09], p= 2.665 × 10−3) and multiple sclerosis (3.42 [1.67, 6.02], p = 9.681 × 10−4) are associated with a NOTCH3 cysteine-altering variant in any domain." (PMID 37834922, 2023).
myocardial infarction (5 papers, 2015 to 2024). Gross necrosis of the myocardium, as a result of interruption of the blood supply to the area, as in coronary thrombosis. "APL13/APJ system causes up-regulation of Notch3 in post-myocardial infarction." (PMID 29254197, 2017). "In summary, our results suggest that ELA activates VEFG/VEGFR2 and Jagged1/Notch3 pathways through APJ to promote angiogenesis after myocardial infarction." (PMID 34291565, 2021). "The results suggest that ELA activates VEFG/VEGFR2 and Jagged1/Notch3 pathways through APJ to promote angiogenesis after myocardial infarction." (PMID 34291565, 2021). "Another study has shown that NOTCH3 mutation carriers are at increased risk of early onset myocardial infarction compared to related nonmutation carriers." (PMID 26435852, 2015). "Another study, though in a non-tumor setting of myocardial infarction recovery, illuminated the function of nucleolin (NCL) in regulating the immune response by controlling STAT6 and Notch3 pathways to promote M2 macrophage polarization, underscoring NCL's potential in modulating immune reactions." (PMID 38806553, 2024).
pulmonary fibrosis (5 papers, 2016 to 2026). Chronic progressive interstitial lung disorder characterized by the replacement of the lung tissue by connective tissue, leading to progressive dyspnea, respiratory failure, or right heart failure. "Using a bleomycin-induced model of pulmonary fibrosis, they reported that NOTCH3-deficient mice were protected from bleomycin-induced pulmonary fibrosis." (PMID 34831437, 2021). "Conversely, the loss of Notch3 slows the progression of pulmonary fibrosis." (PMID 41481554, 2026). "Deletion of NOTCH3 has been shown to significantly reduce the onset and progression of pulmonary fibrosis, suggesting a potential target for IPF treatment." (PMID 41481554, 2026). "Our findings in the present study revealed that the reduction in nestin and Notch3 co-expressing lung endothelial cells were involved in the initiation of pulmonary fibrosis." (PMID 37735673, 2023). "The decrease in both nestin and Notch3 expression during pulmonary fibrosis was verified using bleomycin-induced pulmonary fibrosis in nestin-GFP mice." (PMID 37735673, 2023). "Thus, targeting ERK1/2 signaling for activation and p38, JNK1/2 and Notch3 for inhibition may be of clinical potential against lung fibrosis." (PMID 27248323, 2016).
rheumatoid arthritis (5 papers, 2022 to 2025). A chronic, systemic autoimmune disorder characterized by inflammation in the synovial membranes and articular surfaces. "The proportion of CD34-THY1+ fibroblasts in RA synovial tissue is significantly higher than that of other fibroblasts, which may be an essential pathologic subgroup in rheumatoid arthritis, with upregulated NOTCH3 signaling pathway for contribution in parietal cells and auto differentiation." (PMID 36465169, 2022). "Finally, comparative analysis with rheumatoid arthritis reveals JIA-enriched cell states, including NOTCH3+ and CXCL12+ sublining fibroblasts, suggesting potentially differential inflammatory programs in pediatric versus adult arthritis." (PMID 40894156, 2025).
small cell lung carcinoma (5 papers, 2021 to 2025). Small cell lung cancer (SCLC) is a highly aggressive malignant neoplasm, accounting for 10-15% of lung cancer cases, characterized byrapid growth, and early metastasis. "However, the expression of Notch3 in small-cell lung cancer was lower than that in the normal lung tissues." (PMID 34234838, 2021). "In small-cell lung cancer (SCLC), the prevalence of loss-of-function mutations of Notch proteins is reported to be about 25–28%, with Notch1 being the most frequently mutated, followed by Notch2, Notch4, and Notch3." (PMID 39766289, 2024).
T-cell lymphoma (5 papers, 2009 to 2024). "In Notch3-dependent T-cell lymphoma, PKCθ expression was correlated with NF-κB activation and survival, with deletion of PKCθ leading to reduced incidence of disease in transgenic mice." (PMID 38752473, 2024). "For example, it is a downstream player in pre-TCR-Notch3 signaling where its activation of NF-κB is responsible for the development of Notch3-dependent T-cell lymphoma." (PMID 26090489, 2015). "Moreover, the NF-κΒ pathway may be involved in the development of Notch3-dependent T-cell lymphoma in humans, and there is genetic and biochemical evidence that Notch3 triggers multiple NF-κΒ activation pathways." (PMID 22128846, 2011). "In addition, NOTCH3 mRNA has also been noted in patients with T cell lymphoma, and thymocyte-specific NOTCH3IC transgenic mice develop T cell lymphoma of the spleen and lymph nodes." (PMID 25759795, 2015).
Alagille syndrome (4 papers, 2014 to 2025). "For example, except for the common disease gene JAG1 between Tetralogy of Fallot and Alagille syndrome, the two diseases interact through 5 PPIs with a p value < < 0.01 in the network, including JAG1 – NOTCH1, JAG1 – NOTCH2, JAG1 – NOTCH3, DLL1 - NOTCH2 and DLL1 – NOTCH3." (PMID 25539592, 2014).
cerebral infarction (4 papers, 2015 to 2025). An ischemic condition of the brain, producing a persistent focal neurological deficit in the area of distribution of the cerebral arteries. "Therefore, the atypical mutation of the NOTCH3 gene may have led to the impairment of microvascular regulation and consequently led to the development of white matter lesions and the cerebral infarction." (PMID 25834748, 2015). "Tian and Wang concluded that acupuncture can inhibit apoptosis of cerebral infarction neurons by stimulating Notch3 signaling pathway and triggering corresponding protein expression." (PMID 38608052, 2024).
Cirrhosis (4 papers, 2017 to 2022). A chronic disorder of the liver in which liver tissue becomes scarred and is partially replaced by regenerative nodules and fibrotic tissue resulting in loss of liver function. "One subject with advanced fibrosis/cirrhosis had a mutation in the proline–glutamic acid–serine–threonine (PEST) domain (p.P2034fs) of NOTCH3, which leads to activated NOTCH signaling and a subsequent oncogenic event." (PMID 34299031, 2021). "miR-571 is involved in the inflammatory process in cirrhosis, and can regulate the activation of human stem stellate cells by mediating the Notch3 signaling pathway." (PMID 35720085, 2022). "Yet, we observed that Jag1, Notch 1, Notch 2, Notch 3, and Hey2 were significantly upregulated in both Ep+CIR and Ep+HCC cells as compared to Ep+NSCs, indicating the appearance of CSC like phenotype during advanced cirrhosis." (PMID 28176469, 2017).
colon adenocarcinoma (4 papers, 2017 to 2024). "Colon adenocarcinoma patients with a higher mRNA expression of Notch3, Notch4, and Hey1 presented significantly a shorter overall survival compared to those with low expression." (PMID 32211044, 2020). "In contrast to previous reports, in this study we were able to detect APL13, APJ, and Notch3 in normal epithelial tissues, albeit at significantly lower levels than in colon adenocarcinoma." (PMID 29254197, 2017). "Fibroleukin (FGA) and NOTCH3 are vital in both exercise-induced muscle adaptation and colon adenocarcinoma (COAD) progression." (PMID 39130639, 2024). "Further investigation into NOTCH3 expression in colon adenocarcinoma (COAD) showed significant positive correlations with CD4+ T cells, macrophages, neutrophils, and dendritic cells." (PMID 39130639, 2024).
cyst (4 papers, 2018 to 2022). A sac-like closed membranous structure that may be empty or contain fluid or amorphous material. "To evaluate Notch3’s effect on proliferation and cyst formation, we measured proliferation using PCNA and MCM-2." (PMID 35055068, 2022). "Data from ARPKD and ADPKD mouse models and ADPKD patients indicate that Notch3 is consistently upregulated in cyst-lining epithelial cells." (PMID 33149805, 2020). "In contrast, in mouse models and patients with ADPKD, Notch3 is upregulated in cyst-lining epithelial cells." (PMID 33149805, 2020). "We hypothesized that Notch3 plays a crucial role in cyst formation." (PMID 35055068, 2022). "We also found a similar increase in Notch3 in patients with ACKD, suggesting a common mechanism that activates Notch3 during cyst formation." (PMID 35055068, 2022). "Importantly, Notch inhibition significantly decreased forskolin-induced Notch3 activation and proliferation of primary human ADPKD cells, and significantly reduced cyst formation and growth of human ADPKD cells cultured in collagen gels." (PMID 29463793, 2018). "Thus our data indicate that Notch3 is aberrantly activated and facilitates epithelial cell proliferation in PKD, and that inhibition of Notch signaling may prevent cyst formation and growth." (PMID 29463793, 2018).
fibrosis (4 papers, 2012 to 2023). the formation of excess fibrous connective tissue in an organ or tissue in a reparative or reactive process. "The 50 mg/kg dose of DAPT significantly reduced the protein levels of Notch3-ICD and Hes1 as compared with fibrosis group (P<0.05)." (PMID 23056328, 2012).
metastatic disease (4 papers, 2012 to 2023). "When patients with metastatic disease were compared to those with locally advanced disease, only cytoplasmic expression of Notch3 differed significantly between the groups, being higher in those patients with distant metastases (p = 0.018)." (PMID 23226563, 2012). "Our findings provide with important insight into HNSCC pathogenesis, suggesting that metastatic cells acquire dependency on Notch3 signaling that may be amenable to targeting metastatic disease." (PMID 37202533, 2023). "Our data suggest that inhibition of Notch3 signaling, and in particular, the Jag2/Notch3/Hey1 axis may be an effective therapy for HNSCC metastatic disease." (PMID 37202533, 2023). "Taken together, our data indicate that Notch3 is an essential gene for survival and proliferation of metastatic HNSCC cells in vitro and in vivo and targeting this pathway has therapeutic potential in patients with metastatic disease." (PMID 37202533, 2023).
Osteopenia (4 papers, 2021 to 2025). Osteopenia is a term to define bone density that is not normal but also not as low as osteoporosis. "We created a mouse model (Notch3em1Ecan) harboring a 6691TAATGA mutation in the Notch3 locus, and heterozygous Notch3em1Ecan mice exhibit cancellous and cortical bone osteopenia." (PMID 35536858, 2022). "The results confirm observations reported in mouse models of LMS termed Notch3em1Ecan that presented with a NOTCH3 gain-of-function and osteopenia secondary to an increase in receptor activator of NF-κB ligand (RANKL) in cells of the osteoblast lineage." (PMID 39752389, 2025). "We also reported that ASOs targeting either Notch3 or Notch3 mutants replicating the pathogenic variant of LMS, inhibit Notch3 mRNA and improve the cortical osteopenia found in Notch3em1Ecan mice." (PMID 39752389, 2025). "Microcomputed tomography demonstrated that the administration of Notch3 ASOs ameliorates the cortical osteopenia of Notch3em1Ecan mice, and ASOs decreased femoral cortical porosity and increased cortical thickness and bone volume." (PMID 35536858, 2022). "Previously, we have shown that anti-NOTCH3 NRR antibodies reverse the osteopenia of Notch3em1Ecan mice." (PMID 33774049, 2021). "Therefore, the effect of Notch3 ASO was limited to the cortical bone osteopenia, possibly because Notch3 is preferentially expressed by the osteocyte and cortical bone is enriched in these cells." (PMID 35536858, 2022). "In conclusion, Notch3 ASOs downregulate Notch3 expression in skeletal cells and their systemic administration ameliorates cortical osteopenia in Notch3em1Ecan mice; as such ASOs may become useful strategies in the management of skeletal diseases affected by Notch gain-of-function." (PMID 35536858, 2022). "However, the administration of Notch3 ASOs did not ameliorate the cancellous bone osteopenia of Notchem1Ecan mice." (PMID 35536858, 2022). "However, Notch3 ASOs did not modify the cancellous bone osteopenia of Notch3em1Ecan mice at either femoral or vertebral sites." (PMID 35536858, 2022).